HMGB1 (high mobility group box 1)
Diseases named in the same sentence as HMGB1 in open-access papers (continued):
Sharing a sentence is not in itself a finding about the gene and the disease.
tumor (continued). "The CRT protein was upregulated in the 43 °C nanoinhibitor group compared with other groups, and increased HMGB1 were released into the tumor microenvironment." (PMID 37316830, 2023). "The release of HMGB1 in a tumor microenvironment can be also elicited both by hyperthermia and hypoxia, but hyperthermia was shown to exert a stronger effect." (PMID 37511951, 2023). "In this study, we developed Lf-GL with a high binding affinity for HMGB1 that acts as a tumor-promoting cytokine and is involved in angiogenesis and tumor progression in the tumor microenvironment." (PMID 37210579, 2023). "We assessed the concentrations of proinflammatory factors (IL-1β, IL-18, HMGB1) in tumours or in serum." (PMID 37673934, 2023). "The S100s proteins, histones, amphoterin (HMGB1), or HSPs secreted by tumor cells are recognized by PRRs as DAMPs." (PMID 37106700, 2023). "Correspondingly, the level of HMGB1 and ATP released from the tumor cells was increased significantly after rTCS-LMWP treatment." (PMID 37063415, 2023). "More importantly, Ir1 induced the rise of CRT expression on the tumor cell surface and promote the extracellular migration of HMGB1, demonstrating the ICD." (PMID 37933288, 2023). "High expression of HMGB1 produces the tumor-promoting role in HCC, which was capable of enhancing the growth and metastasis of HCC." (PMID 38025527, 2023). "Dendritic cells are recruited to dying tumor cells by ATP, engulfing tumor antigens when stimulated by calreticulin and presenting tumor cell antigens to T cells when stimulated by HMGB-1." (PMID 36982933, 2023). "Researchers further found that HMGB1 was released by tumor cells after radiation therapy, and HMGB1 promoted NET formation by activating TLR4 signaling." (PMID 36993957, 2023). "Extracellular HMGB1 has been shown to participate in tumor formation and metastases, acting as a pro-tumor factor, whereas intracellular HMGB1 exhibits pro-autophagic activity, promoting cancer progression and increasing drug resistance." (PMID 37511951, 2023). "In the tumor angiogenic environment, HMGB1 is known to act as a proinflammatory cytokine that stimulates the expression of vascular endothelial growth factor (VEGF) and triggers migration and sprouting of endothelial cells." (PMID 37210579, 2023). "HAVCR2 inhibits anti-tumor immunity by interacting with its ligand Galectin 9 (Gal9), phosphatidylserine (Ptdser) high mobility group box 1 (HMGB1), and carcinoembryonic antigen-related cell adhesion molecule 1 (CEACAM1)." (PMID 37005667, 2023). "HMGB1 acts as an anti-tumour protein, regulating the immune cell response during the process of carcinogenesis, with the implication that abnormal HMGB1 expression is associated with the oncogenesis, development and metastasis of cancer." (PMID 37298365, 2023). "HMGB1 induces apoptosis in monocyte-lineage immune cells and inhibits tumor-infiltrating macrophages and dendritic cells, lymph node sinus macrophages and liver Kupffer cells to attenuate anti-cancer immune responses, and anti-metastatic organ defense." (PMID 37110415, 2023). "Elevated HMGB1 in tumor cells has been correlated with tumor formation, cell proliferation and metastasis, and chemotherapy response." (PMID 37518006, 2023). "As for the role of HMGB1 in tumor, HMGB1 demonstrates dual functionalities in the context of cancer progression and treatment." (PMID 37828579, 2023). "HMGB1 knockdown inhibited tumor cell proliferation, but HMGB1 knockdown had little ameliorative effect on the tumor promotion caused by circHERC1 overexpression." (PMID 37932766, 2023). "The platelet activation can be caused by numerous factors, for example, cytokine mediation or secretion of soluble mediators like ADP, thromboxane A2 (TXA2), or high-mobility group box 1 (HMGB1) by tumor cells." (PMID 37673810, 2023).
tumor (continued). "Another study showed that human NSCLC cells with reduced expression of RAGE and hence limited signaling via HMGB1 have a reduced growth rate relative to tumor cells with higher expression of RAGE." (PMID 36831371, 2023). "All these findings suggested that the mutual regulation of HMGB1 and circRNAs plays an important role in the development of tumor cells." (PMID 38025527, 2023). "After 28 days, overexpression of HMGB1 remarkably promoted tumor growth, while the tumor volume of A549-DDP-si-HMGB1 mice was smaller than that of A549-DDP group." (PMID 37518006, 2023). "Specifically, the authors showed that TIM-3 was predominantly expressed by TADCs and interacted with HMGB1, suppressing nucleic acid-mediated activation (preventing localisation in endosomal vesicles) of an effective anti-tumour immune response." (PMID 36980583, 2023). "Anti-tumor effects of HMGB1 are produced through its interaction with tumor suppressor factors or increasing genome stability and autophagy." (PMID 37110415, 2023). "GSDME‐mediated pyroptosis accelerates the progression of CAC by releasing HMGB1, which stimulates tumor cell proliferation and PCNA expression via the ERK1/2 pathway." (PMID 37752941, 2023). "The oxidative tumor microenvironment (TME) favors the oxidation of HMGB1 leading to the formation of diverse oxidized forms." (PMID 36674798, 2023). "While para-cancerous non-tumor tissues always displayed nuclear HMGB1 immunoreactivity, positive cytoplasmic expression of HMGB1 was detected in nearly half of the analyzed HCC tissues." (PMID 37554278, 2023). "These secretion processes predominantly take place in damaged or impaired cells, inflammatory environments and highly proliferating tumor tissue, although HMGB1 is present in a variety of physiologically occurring tissues." (PMID 37894448, 2023). "The HMGB1 released from the necrotic tumor executes alarmin functions, activating tumor growth signaling via binding to a variety of receptors including TLR2/4, RAGE, and C-X-C motif chemokine receptor 4 (CXCR-4)." (PMID 37210579, 2023). "As previously discussed, the escalation of molecules such as HMGB1, HSP70, S100A8/A9, or HMGB1+ tumor cells, or EVs carrying HMGB1, HSP70 and HSP90 in the TME, is closely associated with M1 polarization, maturation of DCs, or the recruitment of TANs." (PMID 37833255, 2023). "Inhibition of tumor angiogenesis and development by Lf-GL attenuating HMGB1 action in the tumor microenvironment was comprehensively evaluated through in vitro, ex vivo, and in vivo." (PMID 37210579, 2023). "The process of calreticulin translocation to the surface of tumor cells treated with certain therapeutic factors involves the secretion of ATP, Hsp70/90 and HMGB1 into the medium." (PMID 37880798, 2023). "HMGB1 is an intriguing molecule and appears to play an important role in tumor biology, inflammation, and cancer progression." (PMID 37626858, 2023). "Cancer-associated fibroblasts have been identified as promoters of tumor metastasis in NSCLC and inducers of doxorubicin resistance in breast cancer by increasing HMGB1 production." (PMID 38066523, 2023). "HMGB1 also induces immunosuppression and tumor progression, in which tumor cells secrete HMGB1, and Treg and monocyte cell suppression is promoted." (PMID 37817484, 2023). "Exposure of calreticulin (CRT) on the surface of tumor cells together with the release of high-mobility group box 1 (HMGB1) and secretion of adenosine triphosphate (ATP) are considered the main markers for ICD." (PMID 37226233, 2023). "GSC transfer lncRNA MALAT1 (nuclear-enriched abundant transcript 2, NEAT2) cells into microglia in an EVs manner and regulate inflammatory responses mediated by the miR-129-5p and HMGB1 cascade to achieve pro-tumor effects." (PMID 37700840, 2023). "We previously reported that histotripsy tumor ablation results in the widespread translocation of DAMPs like HMGB1 and calreticulin within the ablation zone." (PMID 36756111, 2023).
tumor (continued). "TTFields can also induce immunogenic death of tumor cells, leading to the release of danger signals such as HMGB1, ATP, and calreticulin, which activate dendritic cells and promote CD45+ leukocyte enrichment." (PMID 37916157, 2023). "Taken together, Lf-GL efficiently targeted the GBM through interactions with LfR, inhibited GBM cell proliferation and growth, and arrested HMGB1, which is considered as a key factor for tumor growth and angiogenesis." (PMID 37210579, 2023). "The exodus of high mobility group box 1 (HMGB1) late in the course of ICD triggers Toll-like receptor 4 (TLR4)-mediated tumor antigen processing and ultimately drives DC maturation." (PMID 37907944, 2023). "Consistent to clinical view, in our study, necrotic tumor cells sustainedly secreted HMGB1 and triggered cascade response, leading to persistent necrosis of the lesion." (PMID 37210579, 2023). "Tumor cell migration and invasion, a critical factor in tumor progression and metastasis, were effectively attenuated in the presence of HMGB1." (PMID 37210579, 2023). "HMGB1, proven to be a tumor suppressor, is normally responsible for DNA organization and transcriptional regulation." (PMID 37305384, 2023). "Regarding the tumor microenvironment, Lf-GL inhibits angiogenesis and tumor growth by blocking HMGB1 released from necrotic tumors and preventing recruitment of vascular endothelial cells." (PMID 37210579, 2023). "HMGB1, which can be massively released within the tumor microenvironment, plays paradoxical roles in cancer depending on its localization." (PMID 37446102, 2023). "HMGB1 is involved in several cellular processes, including inflammation, tumor progression and cell differentiation." (PMID 37222533, 2023). "Behalf of the high binding affinity to HMGB1, Lf-GL (1:10) exerted dominant antitumor activity in both 2D and 3D tumor cell spheroid culture system." (PMID 37210579, 2023). "TLR2 is expressed in tumor-associated macrophages (TAM) of HCC and contributes to autophagy in the regulation of M2 macrophage polarization by high-mobility group box 1 (HMGB1)/NADPH oxidase 2 (NOX2) axis." (PMID 37020586, 2023). "These DAMPs include calreticulin, which is exposed to the cell surface, high mobility group box 1 (HMGB1), which is secreted by tumour cells as well as ATP molecules and heat shock proteins (HSP70 and HSP90)." (PMID 37600799, 2023). "Irradiation is known to induce immunogenic cell death characterized by releasing of tumor antigens and damage-associated molecular patterns (DAMPs) such as HSP70, HMGB1, and calreticulin." (PMID 36545361, 2023). "Taken together, our results show that circ-YES1 promotes tumor development through the miR-142-3p–HMGB1 axis and support the development of circ-YES1 probability as a new therapeutic NSCLC target." (PMID 37009887, 2023). "We found that several DAMP-related genes, including Hmgb1, Calr, and Anxa1, were significantly overexpressed in Ero1aKO tumor cells compared with WT controls, suggesting the intracellular danger signaling pathways that govern ICD in Ero1aKO tumors." (PMID 37769655, 2023). "At the early stage of YUMM3.3 tumor growth examined here, Activin-A secretion increased the expression of the ligands Lgals3, Hmgb1, Lgals9, CD274 in various cell types." (PMID 38304252, 2023). "Inspired by this point, we analysed the inflammation in TIOs+NIR1 treated mice, as shown, compared with TIOs+NIR3 treatment, the IL-1β, IL-18 and HMGB-1 release in tumour beds were almost four fifths lower." (PMID 37673934, 2023). "The oncolytic peptides DTT-205 and DTT-304 induced calreticulin exposure and HMGB1 release, promoting tumour remission and the development of long-term immune memory against sarcoma and lung cancer cells in vivo." (PMID 38077402, 2023). "Tumor-specific T cells are drawn to tumors by the biomarkers associated with ICD, such as calreticulin, high-mobility group box 1, and ATP33." (PMID 37932362, 2023).
tumor (continued). "PT triggers immunogenic cell death (ICD) that will release tumor-specific antigens (TSAs) and damage-associated molecular patterns (DAMPs), namely CRT, HMGB-1, and ATP." (PMID 37238966, 2023). "After tumor cells are stimulated, classical protein kinases and calmodulin-dependent protein kinases are activated to stimulate HMGB1 metastasis." (PMID 37518006, 2023). "To this end, we constructed tumor microenvironment-mimic model to investigate the restriction effect of Lf-GL on HMGB1, which plays a critical role in crosstalk between tumor and endothelial cells." (PMID 37210579, 2023). "Conversely, HMGB1 exhibits a protective function in inhibiting tumor progression and enhancing the efficacy of tumor chemoradiotherapy and immunotherapy." (PMID 37828579, 2023). "It has been proposed that HMGB1 secreted by cells undergoing ICD activates dendritic cells to cross-present tumor neoantigens to lymphocytes, which elicit B- and T-cell responses." (PMID 37110415, 2023). "Hmgb1 is a damage-associated molecular pattern (DAMP) and its release by tumor cells facilitates immunogenic cell death (ICD)." (PMID 37582744, 2023). "HMGB1 released from necrotic tumor cells, a natural phenomenon in tumor development, is expected to be highly involved in angiogenesis and tumor cell progression." (PMID 37210579, 2023). "Numerous reports have previously shown that oHSV treatment of tumor cells results in the release of HMGB1 in the extracellular environment." (PMID 36789106, 2023). "Conversely, one HMGB1 upregulated tumour, THYM, presented a slightly upregulated DNA methylation level." (PMID 35765707, 2022). "As a protective reaction to irradiation tumor cells increase surface expression of various plasma membrane proteins, including HSPs and high-mobility group box 1 (HMGB1)." (PMID 36544712, 2022). "The expression levels of the genes positively associated with anti-tumor immunity, such as CD8, interferon-γ (IFN-γ), and perforin, in the HMGB1-knockout tumor tissues were higher than those in the WT tumor tissues." (PMID 35150340, 2022). "None of the eight patients with increasing HMGB1 levels during therapy experienced tumor recurrence according to our follow-up data, while all three patients with declining HMGB1 levels showed local and/or distant treatment failure." (PMID 34671818, 2022). "MiR-216 is another tumor suppressor that inhibits angiogenesis by targeting high mobility group box 1 (HMGB1)." (PMID 36286020, 2022). "Similar to cytokines, HMGB1 plays an important role in the cancer progression and also induces immune tolerance in the tumor microenvironment by chronic inflammation." (PMID 35829833, 2022). "Transwell experiments were used to study migration of B cells in response to recombinant HMGB1 (rHMGB1) or in the presence of HMGB1-overexpressing tumor cells." (PMID 34617194, 2022). "In fact, immunocytochemical analysis revealed upregulated VEGF production in B cells when co-cultured with HMGB1-overexpressing tumor cells." (PMID 34617194, 2022). "Using the median fold change in HMGB1 expression as the cut-off point (Tumor to Normal ratio, T/N = 1.374), patients were divided into a high HMGB1 expression group (T/N fold change > 1.374) and a low HMGB1 expression group (T/N fold change < 1.374)." (PMID 34617194, 2022). "Our results herein demonstrate that CRC cells respond to oHSV expressing HMGB1 differently, which is likely dependent on the profile of the tumor cell microenvironment and tumor cell type itself." (PMID 35477503, 2022). "ICD is mainly characterized by calreticulin (CRT) exposure at the cell surface of dying tumor cells, the release of the ATP, HMGB1 (High-Mobility Group Box 1) and annexin A1 (ANXA1) in the extracellular space." (PMID 36429101, 2022). "After being released from inflammatory cells, necrotic cells, or tumor cells, extracellular HMGB1 can bind to pattern recognition receptors and induce inflammation or promote tumor progression." (PMID 35280439, 2022).
tumor (continued). "In tumor cells, moreover, it has been reported that HMGB1 can bind mitochondrial DNA (mtDNA) released following hypoxic stimuli and activates toll like receptor 9 pathway to promote cellular proliferation." (PMID 35053332, 2022). "In the present study, we established HMGB1-knockout clones from B16F10 and CT26 murine tumors by genome editing using the CRISPR/Cas9 system and investigated the role of HMGB1 in anti-tumor immunity." (PMID 35150340, 2022). "DAMPs, including HMGB1, are thought to be an initiator of DC maturation and subsequent anti-tumor immunity." (PMID 35150340, 2022). "Next, we demonstrated that ERK and p38 MAP kinase were activated (by phosphorylation) and involved in the promotion of VEGF expression in B cells via tumor-derived HMGB1 and the induction of VEGF was attenuated by the presence of GL." (PMID 34617194, 2022). "The secondary signals from tumor- and tumor stroma-derived factors including HMGB1, TLRs, TGFβ, and endoplasmic reticulum (ER) stress then pathologically activate MDSCs through STAT6, STAT1, and NF-κb signaling pathways." (PMID 36031601, 2022). "It is noteworthy that in the tumor microenvironment, HMGB1 has been demonstrated to induce migration and prolong survival of Treg." (PMID 35053332, 2022). "The mice treated with 25 mW of micro-LED revealed significantly increased CRT-positive tumor cell (CD45−CRT+) population and HMGB1 in the tumor tissues compared to other groups." (PMID 36258234, 2022). "HMGB1 secreted by dying tumor cells triggers the activation of IFN-γ polarizing tumor-antigen specific T-cells through a TLR4- and MyD88-dependent mechanism." (PMID 35493517, 2022). "We showed that plasma HMGB1 increased in the early response stage and was stably detected during tumor regression for at least 8 days." (PMID 35336794, 2022). "When tumor cells are stimulated by physical, chemical, biological and other factors, HMGB1 can be rapidly transferred to the cytoplasm." (PMID 36335371, 2022). "Archival tissues from a total of 118 paired tumor/adjacent normal cases were selected to evaluate HMGB1 expression." (PMID 34617194, 2022). "To investigate the function of HMGB1 in GB patients, we analyzed mRNA levels of HMGB1 in GB and non-tumor tissues from the TCGA-GBM and Rembrandt dataset." (PMID 35193644, 2022). "The authors demonstrated that P. aeruginosa 1409 induced a programmed necrosis (necroptosis) of TC-1 tumor cells through activation of TLR4-RIP3-MLKL, and the HMGB1 released by the dying tumor cells further induced DC maturation and migration to tumor sites." (PMID 35574361, 2022). "By contrast with previous studies, the present study demonstrated the suppressive effect of HMGB1 on infiltration of immune cells into the tumor microenvironment." (PMID 35150340, 2022). "High mobility group box 1 (HMGB1) plays an essential role in tumor cell proliferation, migration, and cell cycle progression." (PMID 35812184, 2022). "VEGF expression in proliferating B cells was induced upon co-culture of HMGB1-overexpressing tumor cells and B cells." (PMID 34617194, 2022). "Abundant studies have confirmed the involvement of HMGB1 in multiple hallmarks of cancers, making HMGB1 a promising target to combat tumor progression, invasion, metastasis, and chemoresistance." (PMID 35211417, 2022). "In ICD, injured cancer cells, in addition to releasing tumor antigens, release various danger signals including high mobility group box 1 (HMGB1), calreticulin (CRT), heat shock protein (HSP) 90, HSP 70, and adenosine triphosphate (ATP)." (PMID 35740662, 2022). "To confirm the dual effect of HMGB1-fl and HMGB1-ΔC on tumor cells, we first measured the influence of both forms of HMGB1 on the mitochondrial membrane potential (Δψm)." (PMID 35887213, 2022). "In this study, we unified several publicly available databases to investigate the expression of the HMGB1, explored correlations with prognosis and evaluated potential mechanisms of regulation in tumour patients." (PMID 35765707, 2022).